CYP2E1 (cytochrome P450 family 2 subfamily E member 1)
Diseases named in the same sentence as CYP2E1 in open-access papers (continued):
Sharing a sentence is not in itself a finding about the gene and the disease.
liver disease (47 papers, 2006 to 2025). "In hepatocytes, CYP2E1-mediated oxidative stress constitutes a fundamental mechanism underlying the pathogenesis and progression of various liver diseases, thus establishing CYP2E1 as a key molecular determinant in oxidative stress cascades." (PMID 39859525, 2025). "Despite these reports, the results of our research appear to contradict the notion that the CYP2E1 promoter methylation pattern is associated with decreased CYP2E1 expression in liver diseases." (PMID 40870038, 2025). "Cytochrome P450 2E1 (CYP2E1)-associated reactive oxygen species production plays an important role in the development and progression of inflammatory liver diseases such as alcoholic steatohepatitis." (PMID 33769703, 2021). "Strong CYP2E1 induction is associated with ethanol energy expenditure, fast ethanol elimination, and alcohol-induced liver disease." (PMID 26284938, 2015). "CYP2E1 induction has been also recognized as a major pathogenic feature of liver disease observed in both alcoholics and nonalcoholics." (PMID 23691094, 2013). "CYP2E1 metabolises several pro-carcinogens including ethanol and, for that reason, most of the research associated with CYP2E1 focuses on its role in liver diseases." (PMID 24207099, 2013). "Consequently, monitoring CYP2E1 metabolic activity is essential for elucidating the mechanisms underlying liver disease development." (PMID 41171730, 2025). "Therefore, it is suggested that A. cardamomum has valuable therapeutic potential for liver disease caused by CYP2E1 expression by decreasing CYP2E1 expression in liver." (PMID 27246748, 2016). "One typical substrate of CYP2E1 is ethanol which is the main cause of various liver diseases." (PMID 25398514, 2016). "High ROS levels, and hence oxidative stress due to increased CYP2E1 protein levels and induced enzymatic activity, are the main causes of various liver diseases associated with chronic alcohol consumption and a variety of other pathophysiological conditions including diabetes type II and obesity." (PMID 24207099, 2013). "Recent investigations have shown that apart from viral factors, CYP2E1 polymorphism might be associated with the increased risk of liver diseases, including that by HEV in northeast India." (PMID 22308156, 2011). "Polyphenols have been employed in the treatment of liver disease, the latter based on the underlying mechanisms implicated principally in improving antioxidant defense enzymes through the mediation of the expression of Nrf-2/cytochrome P450 2E1 (CYP2E1), which improves the inflammatory process." (PMID 38498532, 2024). "The overexpression of CYP2E1 leads to reactive oxygen species (ROS) accumulation and/or activation of carcinogens, which represents a significant contributing factor in liver disease pathogenesis." (PMID 41171730, 2025). "CYP2E1 is critically important in the overall landscape of hepatotoxicity as it plays a central role in the pathogenesis of several liver diseases." (PMID 41323558, 2025). "Patients with underlying liver disease are predisposed to drug-induced liver injury (DILI); patients with NAFLD exhibit an increase in the activity of the CYP2E1, a 1.9–3.1-times diminution in the activity of CYP3A4 in NAFLD, and of NASH, respectively." (PMID 38498532, 2024). "This study demonstrated that CYP1A2, CYP2C19, CYP2D6, and CYP2E1 enzyme activity was differentially affected by the presence of liver disease." (PMID 36901973, 2023). "According to the statistical data, the p-value of compound 7 in cirrhotic patients is less than 0.0001 (p<0.0001), confirming that CYP2E1 is dysfunctional in liver disease." (PMID 37967076, 2023). "Our study supports the concept in the literature that differences between healthy control VOCs and liver disease patients are linked to CYP450, CYP2E1 enzyme, and CYP2B6 isoform activity alteration in the body due to liver injury." (PMID 37967076, 2023).
liver disease (continued). "In particular, major sources of oxidative stress involved in the therapeutic targets of Hyp are derived from CYP2E1 and the downregulation of the expression of antioxidant genes and Nrf2-regulated phase II enzymes occurring in liver disorders." (PMID 35892639, 2022). "In this review, we first recall several critical features of CYP2E1, including regulation of its expression, its role in the biotransformation of endogenous and exogenous molecules and its involvement in different liver diseases." (PMID 35053404, 2022). "We conclude that CYP2E1 has many important physiological functions and is a key enzyme for hepatic carcinogenesis, drug toxicity and liver disease." (PMID 34360999, 2021). "It has been reported that CYP2E1 knock-out mice exhibit ethanol-induced liver disease, and we previously demonstrated that SMSP supplementation restored total antioxidant concentration levels and significantly reduced hepatic malondialdehyde levels." (PMID 32143357, 2020). "While hepatic CYP2E1 elevation is considered essential to the pathogenesis of these liver diseases, our findings in two mouse models of E3 ubiquitin ligase genetic ablation fed a regular lab chow diet, argue that it is not sufficient for triggering NAFLD/NASH." (PMID 33255949, 2020). "Previous research works showed that DAS has successfully inhibited or downregulated the activity of the CYP2E1 enzyme upon administration of GL oil in hepatic disease conditions." (PMID 31505863, 2019). "CYP2E1 and HOGG1 polymorphisms independently correlate with the development of fibrosis, whereas the c2 variant of CYP2E1 correlates with the severity of liver disease and histology activity index." (PMID 27965466, 2017). "Chronic alcohol intake induces the level and activity of CYP2E1 and generates acetaldehyde and free radicals to induce progression of liver diseases to cirrhosis." (PMID 26937962, 2016). "CYP2E1 can also contribute to aggravated progression of liver disease in CHC patients addicted to heavy alcohol consumption." (PMID 27200149, 2016). "Induction of CYP2E1 by HCV core can play a role in liver disease progression, especially in patients addicted to chronic alcohol consumption." (PMID 26035647, 2015). "Elevated levels of CYP2E1 have been largely attributed to the pathogenesis of liver disease in patients with nonalcoholic steatohepatitis (NASH)." (PMID 22452877, 2012). "In this review, we first recall the main features of CYP2E1 including its role in the biotransformation of endogenous and exogenous molecules, the regulation of its expression and activity and its involvement in different liver diseases." (PMID 35053404, 2022). "The progression of liver disease also entailed a decrease in protein abundance of CYP2E1, which significant reduction was observed even in the Child–Pugh class A patients (as the unique downregulated enzyme levels in the early stage of liver failure were seen)." (PMID 34575411, 2021). "The observed reduction of CYP2E1 abundance may contribute to 40% lower chlorzoxazone (CYP2E1 substrate) metabolic ratio observed in patients with moderate-severe liver disease." (PMID 34575411, 2021). "Furthermore, CYP2E1 is one of the most important indicators of drug-induced liver toxicity and liver disease." (PMID 34199606, 2021). "Likewise, CYP2E1 induction exerts important influences on activation of pro-carcinogens and the progressive hepatic disease." (PMID 28963442, 2019). "Most studies on CYP2E1 are in relation to liver diseases including the metabolism of ethanol." (PMID 29362861, 2018). "Furthermore, as revealed by the network pharmacological study, CYP2E1 is a potential target of JGB on liver diseases." (PMID 29414910, 2018). "Enhanced hepatic levels of cytochrome P4502E1 (CYP2E1) may play a key role in the pathogenesis of some liver diseases as CYP2E1 represents a significant source of ROS, such as superoxide anion radical." (PMID 27128904, 2016).
liver disease (continued). "To correlate with the increased H2O2 production we observed with AZT in this study, we also determined the levels microsomal proteins CYP4A and CYP2E1, since these proteins could be potential sources for ROS production in various liver disease models." (PMID 24146933, 2013). "For susceptibility to the hepatic tumor or liver disease, DraI polymorphism adds no more information than CYP2E1 RsaI genotypes." (PMID 23460870, 2013). "We also detail the role of the CYP4A11 and CYP2E1 arachidonic metabolites and their possible functional role in portal hypertension in hepatic cirrhosis and suggest alteration in these pathways may be therapeutic targets in the treatment of chronic liver disease." (PMID 40452921, 2024). "Activities of CYP2E1, CYP2D6, CYP1A2 and CYP2C19 were all found to decrease with increasing hepatic disease severity, their activities were differentially affected." (PMID 27754327, 2016). "We have proposed the hypothesis that CYP2E1 activity is more strongly induced by ADH1B*2-associated fast ethanol metabolism in alcoholics, because this hypothesis explains all of the ADH1B-associated differences in BMI, alcohol metabolism, and the prevalence of advanced liver disease." (PMID 26284938, 2015). "Interestingly, drug-metabolizing enzymes were differentially sensitive towards liver diseases, as evidenced by drastically reduced CYP2C19 activity in patients with mild liver disease, whereas CYP2E1 activity only decreased in decompensated cirrhosis." (PMID 27754327, 2016). "However, in liver disease samples, differential methylation did not consistently translate into decreased CYP2E1 expression." (PMID 40870038, 2025). "As the protein expression and enzyme activity of CYP2E1 are shown to be changed correspondingly in rats, our results suggest that the TAA-metabolizing enzymes are less likely to be involved in the abrogation of liver disease by dietary iron overload in this model." (PMID 30279328, 2018). "Consequently, these combined findings indicate that starting doses of CYP2D6, CYP2E1 and CYP3A4 substrates should be adjusted in patients with moderate or severe liver disease, whereas a dose reduction of CYP2C19 and CYP1A2 substrates should already be considered in milder forms of liver disease." (PMID 27754327, 2016).
alcoholic liver diseases (44 papers, 1997 to 2025). A disorder caused by damage to the liver parenchyma due to alcohol consumption. "CYP2E1 is one of the major ROS generators in the liver and is recognized as a risk factor for alcoholic liver disease." (PMID 33062026, 2020). "CYP2E1 exacerbates alcoholic liver disease through excessive ROS accumulation arbitrated oxidative damage and thereby triggers hepatic cell death." (PMID 38479224, 2024). "As our work demonstrated, DMSO significantly inhibits the activity of multiple enzymes involved in alcohol metabolism, such as ADH and CYP2E1, thereby limiting its utility for the studies of alcoholic liver diseases." (PMID 36607308, 2023). "The most prominent downregulation of metabolizing enzymes was associated with alcoholic liver disease (CYP1A2, CYP2C8, CYP2D6, CYP2E1, CYP3A4, UGT2B7) and primary biliary cholangitis (CYP1A1, CYP2B6, CYP2C8, CYP2E1, CYP3A4)." (PMID 37371728, 2023). "The upregulation of CYP2E1 by HDV infection suggests that this virus can aggravate alcoholic liver disease (ALD), as heavy alcohol consumption is accompanied by an increase in ER mass and the expression of the ER-residing CYP2E1." (PMID 37107349, 2023). "A previous study reported that when rats were given a CYP2E1 inhibitor, either diallyl sulfide or chlormethiazole, hepatic lipid peroxidation was inhibited, and alcoholic liver damage was extenuated." (PMID 36290494, 2022). "In alcoholic liver disease, the higher CYP2E1 levels are thought to be the result of the inhibition of degradation by ethanol." (PMID 36528753, 2022). "CYP2E1 can induce catalytic activity toward alcohol and generate a large amount of reactive oxygen species, which leads to alcoholic liver disease." (PMID 32151025, 2020). "As discussed in Section 3.2, “Target prediction of TCM,” ZZDHT decoction has been applied to treat alcoholic liver disease by targeting CYP2E1, XDH, NOS2, and PTGS2." (PMID 30846939, 2019). "We used TCM-Mesh to validate the effects of ZZDHT, leading to the identification of 12 candidate targets (including CYP2E1) for alcoholic liver disease, all of which were supported by the literature." (PMID 30846939, 2019). "In early-stage alcoholic liver damage, these two enzymes, cytochrome P450 2E1 (CYP2E1) and xanthine oxidase (XO), have been proven to generate ROS in liver as a consequence of alcohol exposure." (PMID 25922610, 2015). "It is known that CYP2E1 has been a focus in alcoholic liver diseases which has been intensively investigated in the past two decades." (PMID 25238230, 2014). "Although CYP2E1 has been extensively studied for many years, lots of this research effort has been focused on its role in drug metabolism and alcoholic liver diseases." (PMID 25238230, 2014). "The oxidative stress generated by increased CYP2E1 promotes alcohol liver disease and liver fibrosis." (PMID 24453428, 2013). "Previous studies have correlated liver damage in NASH or in alcoholic liver disease with increased CYP2E1 isoenzyme activity or expression, thus, suggesting the important role of CYP2E1 in NASH pathogenesis through modulation of fatty acids." (PMID 23320041, 2012). "CYP2E1 is notable for its role in alcoholic liver disease and for its release of reactive oxygen species, which are known to promote fibrogenesis in HSCs." (PMID 21949825, 2011). "Our previous research showed that an LNP-delivered siRNA targeting Cyp2e1 (si-Cyp2e1 LNPs) could effectively inhibit the development of chronic and subacute alcoholic liver disease in mouse models." (PMID 40699771, 2025). "Cytochrome P450 2E1 (CYP2E1) in the microsomal ethanol oxidizing system is a major generator of reactive oxygen species (ROS) in the liver and is considered a significant contributor to alcoholic liver disease." (PMID 39336099, 2024). "Moreover, it was shown that the levels of CYP1A and CYP2E1 were increased in the lymphocytes of patients suffering from tobacco-induced lung cancer and alcoholic liver diseases, respectively." (PMID 38069119, 2023).
alcoholic liver diseases (continued). "CYP2E1 is also a key enzyme in regulating alcoholic liver damage." (PMID 31920652, 2019). "At the post-translational level, SUMOylation, enhancing cyp2e1 protein stability and activity, may have important implications in alcoholic liver disease (ALD)." (PMID 30477109, 2018). "The authors found that ZZDHT may exert antioxidant effects to regulate reactive oxygen species, thereby treating alcoholic liver disease by targeting cytochrome P450 2E1 (CYP2E1), xanthine dehydrogenase (XDH), nitric oxide synthase 2 (NOS2), and prostaglandin-endoperoxide synthase 2 (PTGS2)." (PMID 30846939, 2019). "In the toxic burst hypothesis, alcohol-induced aberrations in hepatic retinoid metabolism results in a toxic burst of transcriptionally active retinoid metabolites, presumable generated by CYP2E1, which directly contribute to the development of alcoholic liver disease." (PMID 22690322, 2012). "Alcohol metabolism by CYP2E1 and increased levels of free iron increase the levels of oxygen radicals.Rats receiving an alcohol-containing diet have reduced glutathione levels in their mitochondria.Patients with alcoholic liver disease have reduced levels of vitamin E." (PMID 15706744, 1997). "Among the top 30 genes in the gene regulatory network, 7 genes are enriched in alcoholic liver disease (hsa04936), including TNF, IL6, IFNA1, CYP2E1, ALDH2, ADH1B, ADH1C." (PMID 38429802, 2024). "Alcoholic mediated SUMOylation enhances alcoholic liver disease development via upregulating CYP2E1, suggesting FAT10 plays a critical role in alcoholic liver disease development (Section 2.1)." (PMID 36386217, 2022). "As such, determination of the true contribution of CYP2E1-mediated ROS formation and effects on the subsequent development of alcoholic liver disease (ALD) has been based on the use of CYP2E1 specific antibodies, knockdowns and CYP2E1 transgenic animals." (PMID 34360999, 2021). "Since CYP2E1 perform an essential role in DILI apart from fatty liver disorder and alcoholic liver damage, the mechanism behind regulation of CYP2E1 induction needs further investigation." (PMID 32735603, 2020). "In contrast, other studies of the diseased liver samples such as hepatocellular carcinoma (HCC), non-alcoholic fatty liver disease (NAFLD), and alcoholic liver disease (ALD) report broad epigenetic alterations but do not provide details on CYP2E1-specific methylation changes." (PMID 40870038, 2025). "Therefore, we suggest that CB1R-ERRγ-FGF23 signal transduction axis plays a pathological role in chronic alcoholic liver injury through regulating CYP2E1 gene expression, and FGF23 may represent a potential therapeutic target to treat alcoholic liver disease." (PMID 38479224, 2024). "Alcoholic liver disease and primary biliary cholangitis were involved in the most prominent changes in the protein abundances, with downregulation of 6 (CYP1A2, CYP2C8, CYP2D6, CYP2E1, CYP3A4, UGT2B7) and 5 (CYP1A1, CYP2B6, CYP2C8, CYP2E1, CYP3A4) significantly downregulated enzymes, respectively." (PMID 34575411, 2021). "Although, the role of CYP2E1 and the microsomal ethanol oxidizing system (MEOS) is well-established in alcoholic liver disease, the role of CYP2E1 in NAFLD is still not clear." (PMID 29874807, 2018). "However, clear differences exist between alcoholic liver disease (ALD)- and NAFLD-induced activation of CYP2E1: while alcohol consumption only stabilizes the CYP2E1 protein without changes in mRNA expression, excessive nutrition increases both protein stability and mRNA abundance." (PMID 32660130, 2020).